IRF4 (interferon regulatory factor 4)
Diseases named in the same sentence as IRF4 in open-access papers (continued):
Sharing a sentence is not in itself a finding about the gene and the disease.
colitis (continued). "Furthermore, upregulating the expression level of Interferon regulatory factor 4 (IRF4) induces the differentiation of macrophages into M2-type macrophages with anti-inflammatory effects and alleviates the symptoms of colitis." (PMID 35873579, 2022). "While this does not formally exclude an ILC-mediated mechanism underlying colitis protection in the absence of IRF4, our and published data, however, are not in favor of the conclusion that regulation of ILC function is here involved." (PMID 33584655, 2020). "In addition, we have shown that whereas MDP administration to WT mice inhibits DSS-colitis such administration does not inhibit DSS-colitis in IRF4-deficient mice." (PMID 36189261, 2022). "To specifically assess whether Th17 cell differentiation inducing and/or Th17 cell promoting cytokines are differentially regulated, we compared colonic gene expression profiles of IL-12 (Th1) and IL-1ß/IL-6/IL-23 (Th17) between colitis-protected Rag1−/−Irf4−/− and colitic IRF4-competent mice." (PMID 33584655, 2020). "Interestingly, cDC2s have been shown to represent a critical source for IL-23 expression in vivo suggesting that especially IRF4 dependent cDC2s might represent critical APC driving Th17 cell responses in vivo as e.g. in the context of colitis." (PMID 33584655, 2020). "In contrast, T cell receiving Rag1−/− mice deficient in IRF4 virtually lacked macroscopic signs of colitis evidenced by a sum score of <3 with a score of ≥3 representing the empiric cut-off value for mice suffering from clinically meaningful, endoscopic signs of colitis." (PMID 33584655, 2020). "The NOD1 expression in T cells could impede the colitis-associated intestinal tumorigenesis through mediating the IFN-γ signaling, and NOD2 could suppress the tumorigenesis of colitis-associated cancer by downregulating NF-κB and MAPK pathways with the induction of IRF4." (PMID 39135979, 2024). "Induced IRF4 expression promoted M2-polarization and ameliorated LPS-induced M1 cytokine secretion, alleviating DSS-induced colitis in mice." (PMID 36767519, 2023). "Genetic deletion of GBP5 in mice showed that mice without GBP5 were more resistant to developing colitis than wild-type littermates, with concomitant regulation of IRF4 phosphorylation and the tight junction marker claudin 2 in their colonic tissue." (PMID 38531874, 2024). "Furthermore, MDP‐induced IRF4 inhibits polyubiquitination of TRAF6 and RICK, thereby reducing NF‐κB expression in a TNBS‐induced colitis model." (PMID 37341064, 2023). "Additionally, IRF4 acts as a negative regulator of TLR4 signalling by modulating cIAP1/2 ubiquitination and expression of inflammatory cytokines in TNBS‐induced colitis." (PMID 37341064, 2023). "Mechanistically, gene profiling experiments revealed a Th17 response dominated molecular expression signature in colon tissues of IRF4-proficient, colitic Rag1−/− but not in colitis-protected Rag1−/−Irf4−/− mice." (PMID 33584655, 2020). "Overall data presented so far unequivocally demonstrate that IRF4 expression within non-T cells is indispensable for T cell mediated transfer colitis in Rag1−/− recipient mice based on both clinical, endoscopic, and histopathological scoring results." (PMID 33584655, 2020). "Conversely, however, the selective role IRF4 expressed by non-T cells exerts in the immune pathogenesis of colitis remains largely unresolved." (PMID 33584655, 2020). "We found that IRF4 expressed in non-T cells is indispensable for the clinical, endoscopic, and histopathological colitis manifestation." (PMID 33584655, 2020). "Reduced colitis activity in the absence of IRF4 was accompanied by hampered T cell expansion both within the mesenteric lymph node (MLN) and colonic lamina propria (cLP)." (PMID 33584655, 2020). "Collectively, our study unequivocally demonstrates that IRF4 expressed in non-T cells is a positive regulator of Th17 cell mediated colitis." (PMID 33584655, 2020).
colitis (continued). "Here, we conversely addressed the impact of IRF4 inactivation in non-T cells on T cell driven colitis in vivo." (PMID 33584655, 2020). "Additionally, colitis‐induced degradation of IRF4 protein in WT mice colonic tissues was not evident in KO mice colonic tissues in acute colitis and early stages of CAC." (PMID 37341064, 2023). "In regard to innate lymphoid cells (ILC) with presumably overall rather colitis-suppressive effects given the fact that ILC depletion leads to enhanced colitis manifestation, we found that the colonic pool of ILC1, ILC2, and ILC3 forms in a virtually IRF4 expression independent manner." (PMID 33584655, 2020). "We could not detect any relative or absolute IRF4-dependent difference within granulocyte subsets and Ly6Chigh monocytes in the absence of T cell induced colitis." (PMID 33584655, 2020). "Since the identification of the precise IRF4-dependent non-T cell immune cell(s) and/or signaling pathways putatively regulating T cell driven colitis was not the focus of this study and in fact will require already planned future experimentation, we can only speculate on that at this point." (PMID 33584655, 2020). "Also, the absolute numbers of CD4+ T cells were significantly diminished within the MLN suggesting that at least to a certain degree hampered systemic T cell activation and expansion may account for the lack of a colitis-mediating T cell pool in the absence of T cell-extrinsic IRF4 expression." (PMID 33584655, 2020).
lupus (14 papers, 2015 to 2025). "More intriguingly, expression of DTA or loss of IRF4 in activated B-1 cells resulted in the production of IgG against protein autoantigens that are less specific for lupus including C1q, collagen, laminin, Gp2, PR3, and MPO." (PMID 41445737, 2025). "Here, we sought to define the role of B-1 cells in the Lyn-/- model of lupus by labeling them and their cellular and antibody progeny, depleting them, and targeting IRF4 in them." (PMID 41445737, 2025). "Murine studies have demonstrated that ROCK2 is activated in Th17 cells and phosphorylates interferon regulatory factor 4 (IRF-4), thus regulating the production of interleukin (IL)-17 and IL-21, two cytokines known to contribute to the pathogenesis of lupus." (PMID 32636749, 2020). "This hypothesis is further supported by mouse experiments demonstrating that the deficiency of Ythdf1 substantially impedes the expression of Irf4, diminishes the proportion of PCs and ameliorates the lupus-like phenotypes." (PMID 41258073, 2025). "Furthermore, mice deficient in DEF6 and SWAP-70 (= Double-knock-out or DKO mice), two members of a unique family of molecules that restrain IRF4 function, spontaneously develop lupus on a C57BL/6 background." (PMID 26544714, 2015). "Thus, DC dysfunction in lupus-prone mice relies on both IRF4-dependent and IRF4-independent pathways." (PMID 26544714, 2015). "In view of the emerging role of IRF4 in lupus pathogenesis, a better understanding of its precise contribution to the broader cellular abnormalities that accompany the development of lupus could provide important new insights into the pathogenesis of this disease." (PMID 26544714, 2015). "Notably, ablation of IRF4 in DKO DCs was effective in ameliorating TLR4- but not TLR9-mediated hyper-responsiveness indicating that DC dysfunction in this lupus model may encompass both IRF4-dependent and IRF4-independent pathways." (PMID 26544714, 2015). "A functional imbalance of IRFs (e.g., IRF5 overexpressing systemic lupus erythematosus (SLE), IRF4 defects and immune dysregulation) has been shown to lead to aberrant macrophage activation and promote autoimmune diseases, chronic inflammation, and tumor progression." (PMID 40529613, 2025). "The minor cluster #11 expressed AXL, IRF4, IRF7, and CD5 genes previously found in AS-DC, Pre-DC, or pDC45,46, but was absent from blood samples; #11 better aligned to transitional DC47 and were mostly observed in HNSCC and in Lupus." (PMID 35418195, 2022). "Given the essential and complex role of IRF4 in innate and adaptive immune responses, it is not surprising that this transcription factor is becoming recognized as a key player in lupus pathogenesis." (PMID 26544714, 2015). "Even more striking was the finding that PDL2 expression on DKO DCs in vivo was largely unaffected by the lack of IRF4 suggesting that compensation between different IRFs may be even more profound in the presence of the complex inflammatory environment observed in lupus." (PMID 26544714, 2015).
Burkitt lymphoma (13 papers, 2013 to 2024). A rare form of malignant mature B-cell non-Hodgkin lymphoma. "Scattered tingible body macrophages were present, at least focally, in 17 cases with IRF4+ tumors, with a conspicuous starry sky pattern reminiscent of Burkitt lymphoma being noted in only one case." (PMID 37081786, 2023). "Forced expression of IRF4 in IRF4-negative Burkitt’s lymphoma cell lines (Daudi and Raji) upregulates plasma cell marker genes, such as CD38 and CD138, and downregulates GCB cell marker genes, such as BCL6 and PAX5." (PMID 36077849, 2022). "Knock-down of IRF4 in a T1 LCL (infected with the Zp-V3-containing Akata strain) induced lytic reactivation whereas over-expression of IRF4 in Burkitt lymphoma cells inhibited both NFATc1 and NFATc2 expression and lytic EBV reactivation." (PMID 35472072, 2022). "Co-transfection of an IRF4 expression vector with the Zp-V3 luciferase vector in EBV-negative BJAB Burkitt lymphoma cells decreased both the constitutive activity, and LMP2A-mediated activation, of the Zp-V3 promoter." (PMID 35472072, 2022). "It has been reported that IRF4 inhibits cell cycle progression of GCB-derived Burkitt's lymphoma cells and induces terminal differentiation toward plasma cells through mechanisms independent of BCL6 downregulation." (PMID 27102442, 2016). "In Burkitt lymphoma (BL) cells, which lack IRF4 expression, EBNA3C may regulate different target genes than in LCLs." (PMID 33720992, 2021). "Expression of IRF4 is associated with resistance to treatment of viral cancers with IFN/AZT, and AZT specifically induces apoptosis as well as initiates the viral lytic program in Type I EBV+ Burkitt’s lymphomas." (PMID 25207815, 2014). "Indeed, low levels of IRF4 in Burkitt lymphoma cells may render the ability of T1 EBNA2 to bind to ets-IRF4 combined elements (EICE sites) of little functional consequence." (PMID 32059024, 2020). "Furthermore, we find that IRF4 over-expression decreases the levels of both NFATc1 and NFATc2 in EBV-positive Burkitt lymphoma cells and inhibits lytic EBV reactivation in response to BCR activation." (PMID 35472072, 2022). "Conversely, over-expression of IRF4 in the EBV-positive Akata Burkitt lymphoma line (which normally expresses no detectable IRF4 protein) decreased constitutive (and BCR-activated) expression of the BZLF1, BRLF1 and BMRF1 lytic proteins." (PMID 35472072, 2022). "We show here that IRF4 knock-down in T1 LCLs infected with Akata EBV promotes lytic EBV reactivation, while over-expression of IRF4 in the Akata Burkitt lymphoma cell line (which do not normally express IRF4) inhibits lytic EBV reactivation." (PMID 35472072, 2022).
Insulin resistance (12 papers, 2018 to 2025). Increased resistance towards insulin, that is, diminished effectiveness of insulin in reducing blood glucose levels. "Experiments with adipocyte-specific Irf4−/− knock outs in mice showed associations with increased weight gain and insulin resistance." (PMID 37672078, 2023). "Myeloid-deficiency of IRF4 results in increased insulin resistance and adipose tissue inflammation when compared to IRF4-competent mice." (PMID 32140136, 2020). "Moreover, interferon regulatory factor 4 (IRF4) plays a crucial role in the ability of MDP to reduce insulin resistance and metabolic inflammation through activation of NOD2." (PMID 39235984, 2025). "Conversely, bacterial cell wall-derived muramyl dipeptide promoted the expression of interferon regulatory factor 4 (IRF4) through NOD2, thereby improving inflammation and insulin resistance in obese mice." (PMID 35242721, 2022). "For example, deletion of the transcriptional regulator Irf4 in Ucp1+ adipocytes disrupts the thermogenic gene program and exacerbates HFD-induced insulin resistance." (PMID 29861389, 2018).
skin cancer (12 papers, 2008 to 2023). "For rs12203592, an intron variant in the IRF4 gene, we observe significantly associated phenotypes related to skin cancer such as actinic keratosis and basal cell carcinoma in the EA GIA analysis, both of which have been identified in previous PheWAS studies." (PMID 36085083, 2022). "Our meta-analysis indicated that the rs12203592 and rs872071 IRF4 gene polymorphisms are associated with individual susceptibility to skin cancer and haematological malignancies." (PMID 24906573, 2014). "The evidence from the present meta-analysis supports the notion that both the rs12203592 and rs872071 IRF4 gene polymorphisms are associated with an individual’s susceptibility to skin cancer and haematological malignancies." (PMID 24906573, 2014). "In this meta-analysis, we included 11 eligible articles comprised of 19 case–control or cohort studies to explore the association between the rs12203592 and rs872071 IRF4 polymorphisms and skin cancer and haematological malignancies risk." (PMID 24906573, 2014). "Overexpression of IRF4 has been well documented in all these cancers but only a few publications have reported the association between IRF4 genetic variants or abnormal expression and skin cancer." (PMID 25207815, 2014). "Research has indicated that the rs12203592 and rs872071 interferon regulatory factor 4 (IRF4) gene polymorphisms correlate with the risk of cancer, especially skin cancer and haematological malignancies, but the results remain controversial." (PMID 24906573, 2014). "It is a known risk factor for skin cancer and has been known to influence IRF4 expression." (PMID 28083618, 2016). "In many more cases, a gene that shows high selectivity is selectively essential within each lineage (e.g., only partial dependence on CTNNB1 in liver, lung, and pancreatic cancers, or on IRF4 in skin cancer)." (PMID 33554860, 2021). "Recent GWAS findings have indicated that variants of the IRF4 gene were associated with the susceptibility to some cancer types, including CLL, HL, NHL, MM and skin cancer." (PMID 24906573, 2014). "Research has demonstrated that IRF4 plays a pivotal role in the development and progression of cancer, particularly in skin cancer and haematopoietic malignancies." (PMID 24906573, 2014). "On the same chromosome, 145.8 kb centromeric from the IRF4 rs12203592, the SNP rs6918152 in the EXOC2 gene was associated with hair color (black to blond) in the initial GWAS, the NHS skin cancer controls, and the Australian samples." (PMID 18483556, 2008). "Additionally, research has revealed that the IRF4 protein is expressed in a wide spectrum of haematological malignancies and skin cancers." (PMID 24906573, 2014). "In our investigation, we demonstrate how the pleiotropic variants, such as the detected SNP-outlier rs12203592 located in an enhancer for the IRF4 gene may help explain the observed relationship between MPB and skin cancers." (PMID 37789011, 2023). "IRF4 and SLC45A2 are pleiotropic for Category A Phenotypes (skin wrinkling and sagging phenotypes), Category B Phenotypes (skin colour phenotypes), and Category C Phenotypes (skin cancer phenotypes)." (PMID 35907981, 2022). "Firstly, when we compared the genetic correlation, and the MTAG results before and after excluding genomic regions (HLA, ASIP, IRF4, MC1R, SLC45A2 and CDKN2A) with very large effect sizes for skin cancers and pigmentation traits, and there was a high concordance." (PMID 36496446, 2022).
COVID-19 (11 papers, 2021 to 2025). A disease caused by infection with severe acute respiratory syndrome coronavirus 2. "We then studied TFs potentially involved in the transcriptomic changes observed in COVID-19 monocytes, using Discriminant Regulon Expression Analysis (DoRothEA), and found that MAF family members, GATA3, STAT4, and IRF4, were associated with upregulated genes in severe COVID-19." (PMID 36443794, 2022). "Our analysis also showed that XBP1 and IRF4 are up-regulated in COVID-19 patients." (PMID 37495990, 2023). "Most striking was the under-expression of genes involved in viral recognition (e.g. TLR7, UNC93B, RIG-I/DDX58), as well as genes encoding downstream signaling molecules and transcription factors (e.g. TRIF/TICAM1, MYD88, IRF7), with the notable exception of IRF4, in COVID-19 compared to INFL." (PMID 34135895, 2021). "The six biomarkers (CCNB1, CDK1, IRF4, LTA, MMP9 and OSM) can be served as the biomarkers for the treatment and prevention of COVID-19." (PMID 40300201, 2025). "Consistent with the bioinformatic analysis, CCNB1, CDK1, IRF4, MMP9 and OSM were significantly overexpressed, while LTA was de-expressed in COVID-19 patients compared with healthy controls." (PMID 40300201, 2025). "The expressions of CCNB1, CDK1, IRF4, MMP9 and OSM were significantly higher in COVID-19 samples compared with matched controls, while LTA was down-regulated in GSE171110 training dataset." (PMID 40300201, 2025). "Although the specific role of IRF4 in the pathogenesis of periodontitis is poorly defined, however, our analysis found that TRF4 was co-upregulated in both periodontitis and COVID-19, and was involved in the immune response process of the two diseases." (PMID 37495990, 2023). "Meanwhile, expression of IRF4 is associated with the secretion of IL-4 and IL-10 which are anti-inflammatory cytokines that may be important to reduce the damage of the cytokine storm in moderate patients and not develop in severe COVID-19 symptoms." (PMID 34603282, 2021). "Of these, nine ISGs were differentially regulated in Asymptomatic versus mild COVID-19 cases; IFNAR2, IRF2BP1, IRF4, MAVS, and TRIM14 were upregulated; whilst IRF2BP2, IRF2BPL, and SOCS3 were downregulated." (PMID 34824360, 2021). "In comparison to the COVID-19(-) PU controls, genes highly expressed in the TV group fell into categories that included neutrophil dysfunction (CD274, PADI2), inhibition of B and T cell responses (CD22, IRF4, ORAI1), and upregulation of pro-inflammatory response pathways (CARD8, MAPK7, IRF7, IFIH1)." (PMID 37026002, 2023).
primary effusion lymphoma (11 papers, 2013 to 2025). A large B-cell lymphoma located in the body cavities, characterized by pleural, peritoneal, and pericardial fluid lymphomatous effusions and that is always associated with human herpes virus-8 (HHV-8). "Pom also induces direct cytotoxicity in primary effusion lymphoma (PEL), a B-cell malignancy caused by KSHV, in part through downregulation of IRF4, cMyc, and CK1α as a result of its interaction with cereblon, a cellular E3 ubiquitin ligase." (PMID 33411730, 2021). "Interestingly, in primary effusion lymphoma, treatment with immunomodulatory drugs also resulted in downregulation of IRF4." (PMID 33812333, 2021). "Disruption of the IKZF1/3-IRF4-MYC transcriptional axis is of specific importance in MM, as studies have shown that in other diseases, such as primary effusion lymphoma, degradation of IKZF1/3 is uncoupled from lenalidomide-induced suppression of IRF4 and MYC." (PMID 34834536, 2021). "It has in fact been shown that targeting the IRF4 network with lenalidomide and the MYC network with BET bromodomain inhibitors has synergistic effects in mantle cell lymphoma and primary effusion lymphoma." (PMID 26731516, 2016).